INS (insulin)
Diseases named in the same sentence as INS in open-access papers (continued):
Sharing a sentence is not in itself a finding about the gene and the disease.
diabetes (continued). "Probiotics have received attention for their possible role in improving glycemic control and insulin sensitivity, particularly in individuals with diabetes or those at risk of developing the disease." (PMID 38931292, 2024). "The mainly cause of diabetes including insulin secretion defect and cells respond poorly to insulin which leading to type 1 diabetes (T1D) and type 2 diabetes (T2D), respectively." (PMID 39627201, 2024). "Diabetes mellitus (DM) is characterized by hyperglycemia due to insulin dysfunction and is associated with many complications." (PMID 39479615, 2024). "These phytochemicals have the potential to lower blood glucose levels, improve insulin sensitivity, and reduce inflammation associated with diabetes." (PMID 38675143, 2024). "Several clinical studies have confirmed that RAAS inhibition can reduce the incidence of diabetes in patients with HF and/or those at risk of coronary artery disease by enhancing insulin sensitivity and secretion." (PMID 39337658, 2024). "Hyperglycaemia that occurs in individuals with type 2 diabetes mellitus is caused by different abnormalities such as an impaired insulin secretion, GCG secretion, glucose uptake/utilisation/reabsorption or lipotoxicity." (PMID 38503901, 2024). "Diabetes is a chronic disease caused by insufficient insulin production or ineffective use of insulin by the body." (PMID 39371832, 2024). "Diabetes impairs glucose and insulin regulation in the human body by causing pancreatic cell damage." (PMID 38371502, 2024). "A Perk knockout mutation in mice leads to the loss of insulin‐secreting beta cells and the development of diabetes mellitus." (PMID 39188936, 2024). "Diabetes is a chronic disease characterized by hyperglycemia, caused by absolute or relative insufficiency of insulin secretion and impaired utilization." (PMID 38998662, 2024). "Further exploration is needed on how impaired brain insulin action contributes to high-risk phenotypes in prediabetes and diabetes, neurological disorders and psychiatric conditions." (PMID 38363340, 2024). "IR is the primary cause for the early onset of diabetes, with the liver serving as the primary site of insulin action and a major contributor to IR." (PMID 39104778, 2024). "Certain genetic variants increase susceptibility to both obesity and diabetes, affecting insulin signaling, adipocyte differentiation, and other metabolic processes." (PMID 39104999, 2024). "The reduced insulin secretion persisted after in vivo implantation in mice, aligning with the increased risk of variant carriers to develop diabetes." (PMID 38743124, 2024). "More than 90% of patients with diabetes worldwide are T2D, which is caused by insulin resistance or impaired producing insulin by pancreatic β cells." (PMID 38297222, 2024). "Sacubitrile–valsartan can be a potent regulator of diabetes-associated metabolic abnormalities and is superior to valsartan alone, which can normalize insulin and glycosylated hemoglobin." (PMID 39444490, 2024). "The American Diabetes Association defines diabetes as a condition marked by the degeneration of insulin- and glucagon-producing cells." (PMID 39598390, 2024). "Type 2 diabetes mellitus is associated with a relative deficit in insulin mainly due to beta cell dysfunction and peripheral insulin resistance." (PMID 38658742, 2024). "Clues into factors that contribute to sex differences in the risk of developing diabetes and diabetes-related complications include a male–female difference in peripheral insulin sensitivity." (PMID 38409052, 2024). "Intravenous Car treatment enhancing insulin sensitivity in T2D aligns with our observation of a high oAcC/Car ratio in diabetes, implying a relative Car deficiency." (PMID 39262573, 2024). "As HNF4α is a transcriptional regulator of the insulin gene, these findings suggest a causal relationship between D248Y and the presentation of diabetes in this family." (PMID 38745825, 2024).
diabetes (continued). "Most recently, a designer glucose-sensitive insulin conjugate-NNC2215 was developed to reduce the risk of hypoglycemia in diabetes treatment." (PMID 39766270, 2024). "The review aimed to identify relevant studies that explored the risk of developing diabetes, prevention and management strategies, and the impact of gut microbiota on glycemic control, insulin sensitivity, and other metabolic parameters." (PMID 39435211, 2024). "In previous studies, the transport of glutamate by VGLUT2 has been demonstrated as the rate-limiting step crucial for the precise regulation of insulin secretion, a process intricately linked to the onset and progression of diabetes." (PMID 38370359, 2024). "Currently, the primary clinical treatment for T2DM relies on oral hypoglycemic drugs and insulin injections." (PMID 39834366, 2024). "This can result in elevated cortisol levels, reduced insulin sensitivity, and increased liver triglycerides, all of which contribute to the risk of gestational and type 2 diabetes mellitus, ultimately leading to fetal macrosomia." (PMID 39156021, 2024). "There is a marked loss in the first phase of insulin secretion in individuals with pre-diabetes and with T1D." (PMID 38979061, 2024). "Patients with diabetes are at risk of developing amyloidomas within the pancreas and at the insulin pump site or very rarely at a distant satellite location." (PMID 39081432, 2024). "Its global prevalence is approximately 14%, with risk factors including obesity, family history of diabetes, advanced maternal age, and ethnicity, which are linked to cellular and molecular disruptions in glucose regulation and insulin resistance." (PMID 39519193, 2024). "These factors collectively contribute to β-cell degeneration and necrosis, potentially leading to reduced insulin secretion and increased risk of diabetes, both insulin-resistant and insulin-dependent types." (PMID 38627360, 2024). "The PIK3R1 gene encodes a p85 regulatory subunit of PI3K, i.e., an essential component of the PI3K enzyme that mediates insulin’s metabolic actions, and its dysregulation has been implicated in the pathophysiology of insulin resistance and diabetes." (PMID 39684804, 2024). "Pancreatitis can lead to diabetes mellitus, where loss of functional or structural β cells and the altered insulin secretion produced by harmed junctional proteins have been described." (PMID 39030443, 2024). "Clinicians must take this seriously because of its high incidence, serious consequences of missed diagnosis, the need for lifelong continuous insulin treatment, related risk of diabetes mellitus complications, and reduced survival." (PMID 39450164, 2024). "Diabetes mellitus (DM) is a group of metabolic diseases characterized by chronic hyperglycemia, caused by defects in insulin secretion and/or utilization." (PMID 38650715, 2024). "The study showed that metformin appeared to decrease the risk of diabetes-related endpoints in overweight diabetic patients with less weight gain and a lower number of hypoglycaemic attacks in comparison to insulin." (PMID 39911238, 2024). "Diabetes mellitus (DM) is a group of common metabolic disorders that share the phenotype of hyperglycemia, which is caused by the demise of insulin secretion, insulin action, or both 1-3." (PMID 38962352, 2024). "By affecting lipid metabolism, insulin sensitivity, and inflammatory responses, S1P impacts risk factors for prediabetes and accelerates the shift from prediabetes to diabetes." (PMID 39777222, 2024). "Research has established an association between diabetes and increased cancer incidence, with elevated insulin and insulin-like growth factor 1 (IGF-1) levels in diabetes and obesity promoting cell growth." (PMID 39594685, 2024). "Diabetes is a complicated chronic illness associated with persistent hyperglycemia due to impaired insulin production, impaired insulin sensitivity or both." (PMID 38961103, 2024).
diabetes (continued). "In patients with Diabetes Mellitus (DM), Enteral Nutrition (EN) is associated with reductions in hyperglycemia and insulin requirements compared to Parenteral Nutrition (PN) treatment." (PMID 39203739, 2024). "Fish is rich in omega-3 fatty acids, which offer various metabolic benefits that enhance insulin sensitivity and reduce the risk of type 2 diabetes mellitus." (PMID 39610877, 2024). "The even chain CAR 4:0, 14:0 and 16:0 are associated with diabetes have been shown to impair insulin signaling and promote oxidative stress in cultured muscle cells." (PMID 38978592, 2024). "In conclusion, we demonstrate that diabetes-associated genetic variation in MTNR1B can raise glucose concentrations through α-cell dysfunction in addition to having effects on insulin secretion." (PMID 39011323, 2024). "Diabetes mellitus is a chronic metabolic disorder characterized by elevated blood sugar levels, primarily caused by insufficient insulin secretion or impaired insulin action." (PMID 39198425, 2024). "There is scope for sulfation pathways to play a role in pancreatic β-cell function and therefore to be linked with the pathogenesis of diabetes or regulation of insulin secretion." (PMID 39290144, 2024). "It has been shown that in patients with diabetes mellitus, intravenous administration of insulin causes elevation of copeptin in the blood that is associated with symptoms of hypoglycemia." (PMID 39769071, 2024). "In the group with diabetes, insulin-treated individuals had the highest risk of long-term mortality." (PMID 39358593, 2024). "The potential associated risk factors were age, family history of diabetes, insulin use during pregnancy, trimester of GDM diagnosis, and hypertension during pregnancy." (PMID 38827883, 2024). "Studies have shown that fibers, especially those that undergo fermentation in the gut, help improve insulin sensitivity, regulate blood sugar levels, and reduce the risk of developing diabetes." (PMID 39734671, 2024). "Among surgically revised patients, female sex and insulin or oral treatment for diabetes mellitus as well as longer operation time were independent risk factors." (PMID 38822404, 2024). "Glucagon mediates severe endogenous hyperglycemia and hyperketonemia in the insulin-deficient state, which is the direct cause of the significantly elevated glucose and ketone levels in patients with severe diabetes." (PMID 39125959, 2024). "Diabetes mellitus (DM) is a chronic metabolic disorder characterized by elevated blood sugar levels arising from defects in insulin secretion, insulin action, or both." (PMID 39687000, 2024). "Typically, a reduction in Mdh2 expression is observed in individuals with diabetes as it can impact insulin release, and Mdh2 mutations have been observed in families that exhibit transgenerational hyperglycemia." (PMID 39000422, 2024). "Among 48 MDM patients with the m.3243A>G mutation, 39.1% had a family history of diabetes, 82.6% had a BMI below 24.0 kg/m2, and 32.6% were receiving insulin treatment." (PMID 39749018, 2024). "Diabetes is a worldwide health problem caused by the loss or dysfunction of the insulin-secreting β-cells in the pancreas." (PMID 38509065, 2024). "Still, some studies suggest a positive association between insulin dose and the risk of malignant neoplasms in diabetes patients; this applies to both human insulin and insulin analogs." (PMID 39457586, 2024). "Advances in insulin technology over the last century, notably the recombinant production of insulin, have dramatically reduced the mortality rate associated with diabetes." (PMID 38703998, 2024). "The associations of diabetes status and its interaction with brain insulin signaling measures with the decline of late-life cognitive function (N=147)." (PMID 38029396, 2024).
diabetes (continued). "Type 2 Diabetes Mellitus (T2DM) is the most common form of diabetes that characterized by an elevated blood glucose concentration associated with body’s impaired response to insulin action, and influences individuals of all demographics." (PMID 38993241, 2024). "SerpinA12 was down-regulated in our COVID-19 patients and is associated with diabetes and obesity due to its insulin-sensitizing effects." (PMID 38760690, 2024). "Adjusted risk of ‘timely basal insulin-initiation’ was more than twofold higher if access to a diabetes nurse (OR = 2.40, [95%CI, 1.68, 3.43]), but related only vaguely to staff size (OR = 1.01, [95%CI, 1.00, 1.03])." (PMID 38116986, 2024). "Diabetes mellitus comprises a group of clinical syndromes characterized by chronic and persistent hyperglycemia caused by defective insulin secretion and/or insulin resistance." (PMID 38377787, 2024). "Advances in diabetes technologies have provided tools that can facilitate self-management in this high-risk group, especially those on insulin therapy with HbA1c values above target." (PMID 38951212, 2024). "One plausible explanation for this correlation is that insulin resistance serves as a shared pathophysiological mechanism underlying both diabetes and hyperuricemia." (PMID 38337727, 2024). "Lower plasma levels of miR-155 were also correlated with diabetic neuropathy, suggesting a role in the pathogenesis of diabetes, potentially impacting insulin resistance and β-cell loss." (PMID 38541714, 2024). "The metabolic disturbances characteristic of diabetes result from a partial or complete deficiency in insulin, a crucial polypeptide hormone responsible for regulating blood glucose levels." (PMID 39727879, 2024). "Insulin delivery faces similar challenges, as the recurring injections which patients with diabetes must endure frequently inconvenience patients and cause them pain." (PMID 38675344, 2024). "Elevated glucose levels are a hallmark of diabetes, a chronic metabolic condition caused by inefficiencies in insulin production or action." (PMID 39238969, 2024). "Together, these processes enhance the risk of diabetes by adversely affecting insulin signaling and glucose homeostasis." (PMID 39449954, 2024). "Continuous glucose monitoring is recommended for people with diabetes using insulin or at increased risk of hypoglycaemia." (PMID 39112642, 2024). "Diabetes mellitus (DM) is a complex metabolic condition defined by chronic hyperglycemia caused by abnormalities in insulin production, action, or both." (PMID 39251658, 2024). "Diabetes mellitus was defined as a self-reported diagnosis with fasting blood glucose (FBG) ≥ 126 mg/dl or HbA1c level ≥6.5%, with insulin or oral hypoglycemic medications, according to the American Diabetes Association (ADA) diagnostic criteria." (PMID 39624218, 2024). "The worsening of insulin sensitivity is a concern, especially in those with risk factors for developing diabetes mellitus (e.g., obesity or a family history of diabetes)." (PMID 39415786, 2024). "In conclusion, this study found that patients with HNSCC or NPC and type 2 diabetes requiring insulin at baseline are at high risk of life-threatening diabetes-related complications whilst undergoing CCRT, particularly if enteral feeding is initiated." (PMID 38392055, 2024). "Meanwhile, in T2DM, the TYK2 promoter variant was linked to an increased incidence of diabetes and associated with dysfunctional insulin production, whereas the T allele of COL4A3 was associated with T2DM with a protective role." (PMID 38926794, 2024). "Losing body weight after induction of diabetes is probably due to the destruction of insulin-producing β-cells by STZ drugs and insulin deficiency." (PMID 39337311, 2024). "Climate change compromised body metabolism, vasodilation, sweating, insulin resistance and cause Type-2 diabetes mellitus and gestational diabetes Mellitus." (PMID 38545021, 2024).
diabetes (continued). "These cytokines promote the decomposition of adipocytes, loss of insulin signaling, and accelerate the development of diabetes." (PMID 38921478, 2024). "This article reviews diverse insulin actions in various organs and the effects of their deficiency on diabetes, its complications, and associated diseases." (PMID 39513056, 2024). "Diabetes associated activities such as adiponectin synthesis, adipokines by adipocytes, insulin signalling and resistance, and diabetic complications, were in line with other databases." (PMID 39281650, 2024). "These mediators consist of the adiposity trait (BMI and WHR), blood pressure trait (SBP and DBP), glucose metabolism-related trait (fasting glucose and fasting insulin), and diabetes (T2D), which are major factors in the causal pathway of education on DKD." (PMID 39193563, 2024). "Diabetic retinopathy is one of the most common microangiopathy in diabetes, essentially caused by abnormal blood glucose metabolism resulting from insufficient insulin secretion or reduced insulin activity." (PMID 38956257, 2024). "As can be seen, those with a TIR % above or equal to 70% had a shorter diabetes duration, lower HbA1C, were less likely to be insulin users, and had a lower risk for severe hypoglycemia." (PMID 39685547, 2024). "A detailed history of each patient’s diabetes treatment, particularly their use of medications that can cause hypoglycemia such as insulin, sulfonylureas, and meglitinides, should be assessed." (PMID 39199594, 2024). "Diabetes mellitus (DM) is a chronic metabolic disease caused by impaired insulin secretion or function and is characterized by chronic hyperglycemia." (PMID 38302943, 2024). "Features seen in patients with obesity and diabetes, such as hyperglycemia, hyperinsulinemia, and the presence of free fatty acids, have been implicated in altering insulin signaling." (PMID 38673503, 2024). "Hyperglycaemia, or elevated blood sugar levels, is a common symptom of diabetes mellitus (DM), a metabolic disorder caused by deficiencies in insulin secretion, insulin action, or both." (PMID 38589438, 2024). "Overall, the evidence for improved outcomes and impact relating to the use of AI and linked DSS in diabetes (particularly beyond glucose control or insulin management) is still emerging, and highly context and system dependent." (PMID 37979006, 2024). "Both insulin-dependent (type 1) and insulin-independent (type 2) diabetes are risk factors for developing lumbar degenerative disease, with severity correlated with duration of the diabetic disease." (PMID 38715931, 2024). "The first injection of insulin to a 14-year-old diabetic patient was applied in 1920, and this treatment finally confirmed the causality link between diabetes and the insulin secretion product of the pancreas." (PMID 39201799, 2024). "Diabetes is a group of metabolic diseases caused by insulin secretion defects or insulin action disorders, primarily characterized by chronic hyperglycemia." (PMID 39483785, 2024). "A reduction in IGF-I and insulin levels has been proposed as a potential cause of neurological disorders in diabetes, as administration of IGF-I can prevent cognitive decline." (PMID 39139399, 2024). "Total BCAA, VAL, LEU and ILE correlated positively with insulin and negatively with diabetes-associated index MATSUDA, which is in line with higher p-BCAAs being related to worsening of glucose metabolism." (PMID 38257154, 2024). "The AOP study identified TCPP and TCEP as key chemicals that cause aberrant glucose metabolism and insulin signaling pathways and result in diabetes." (PMID 39227562, 2024). "Diabetes mellitus is a chronic endocrine disease caused by lipid metabolism disorders or insulin dysfunction." (PMID 38193803, 2024). "Mutations that promote β-cell ER stress and deplete Ca2+ER stores are associated with or cause diabetes (e.g., mutations in ryanodine receptors and insulin)." (PMID 38927260, 2024).